ENSG00000286870 (novel transcript)
Gene: Long non-coding RNA gene on chromosome 3 (197,333,944 to 197,340,706, forward strand). Ensembl gene ENSG00000286870.
Gene Ontology:
Biological process: RNA processing
Cellular component: nucleolus